Y_RNA (Y RNA )
Gene: Miscellaneous RNA gene on chromosome 11 (76,404,140 to 76,404,252, reverse strand). Ensembl gene ENSG00000201756.
Homologues: Orthologues: chimpanzee Y_RNA (99% identical). Paralogues in human: Y_RNA (85% identical), RNY1P5 (84% identical), Y_RNA (84% identical), Y_RNA (82% identical), Y_RNA (81% identical), RNY1P6 (80% identical), Y_RNA (80% identical), RNY1 (79% identical), RNY1P1 (79% identical), Y_RNA (79% identical), Y_RNA (78% identical), RNY1P11 (77% identical), and 92 more.